LINC01133 (long independently transcribed non-coding RNA 1133)
Diseases named in the same sentence as LINC01133 in open-access papers (continued):
Sharing a sentence is not in itself a finding about the gene and the disease.
bladder cancer (2 papers, 2022 to 2023). "In bladder cancer (BC), LINC01133 expression was found to be high in exosomes of the SV‐HUC‐1 human uroepithelial cell line compared to the low expression in BC cells." (PMID 35747817, 2022).
cervical cancer (2 papers, 2021 to 2022). A primary or metastatic malignant neoplasm involving the cervix. "In another context, LINC01133 promotes the progression of cervical cancer by sponging miR-4784 to cause the up-regulation of AT-hook DNA-binding motif-containing protein 1 (AHDC1) promoting EMT." (PMID 34445100, 2021).
lymph node metastasis (2 papers, 2019 to 2025). "There is a significant association between decreased expression of LINC01133 and stage IV LSCC (p=0.0206) as well as the presence of lymph node metastasis (p=0.0203)." (PMID 39744510, 2025).
pancreatic adenocarcinoma (2 papers, 2023). "The findings showed that expression levels of LINC02577, LINC01133 and AC107464.2 in pancreatic adenocarcinoma tissues were significantly higher than in normal tissues (P < 0.05)." (PMID 37173624, 2023). "LINC01133 is highly expressed in pancreatic adenocarcinoma, implying that AC107464.2 which plays a protective role occurs at a low expression level in pancreatic adenocarcinoma." (PMID 37173624, 2023).
periodontitis (2 papers, 2022 to 2024). An acute or chronic inflammatory process that affects the tissues that surround and support the teeth. "Linc01133 expression was dramatically lower in PDL tissues derived from the periodontitis group than that in the healthy group." (PMID 35435112, 2022).
renal cell carcinoma (2 papers, 2022 to 2025). "LINC01133 plays an oncogenic role in RT, particularly in renal cell carcinomas." (PMID 40863724, 2025).
asthma (1 paper, 2022). "The top five AUCs for DElncRNAs of the T2 asthma and healthy control groups included PCAT19 (AUC = 0.949), TP53TG1 (AUC = 0.876), SNHG16 (AUC = 0.852), LINC01133 (AUC = 0.844), and PP7080 (AUC = 0.827)." (PMID 35480331, 2022). "Similarly, the following results showed that the DElncRNAs with the top five AUCs of the T2 asthma and non-T2 asthma groups: PCAT19 (AUC = 0.914), COLCA1 (AUC = 0.827), SLC9A3-AS1 (AUC = 0.824), SNHG16 (AUC = 0.802), and LINC01133 (AUC = 0.793)." (PMID 35480331, 2022).
endometriosis (1 paper, 2021). The growth of functional endometrial tissue in anatomic sites outside the uterine body. "This showed that LINC01133 expression is significantly upregulated in endometriosis lesions compared to eutopic tissue of both patients and controls." (PMID 34445100, 2021). "To evaluate the role of LINC01133 within the epithelial cell compartment of endometriosis lesions, we performed transient siRNAs-based knockdown of LINC01133 in the 12Z endometriosis epithelial cell line, followed by RNA- sequencing." (PMID 34445100, 2021). "We found that LINC01133 is expressed in both stromal and epithelial cells of the eutopic endometrium of women with endometriosis, but appeared to show higher levels in glandular epithelial cells." (PMID 34445100, 2021). "To evaluate the role of LINC01133 in epithelial to mesenchymal transition (EMT) in endometriosis, we further investigated expression of selected EMT regulatory proteins indicated to be differentially expressed in our RNA-seq data." (PMID 34445100, 2021). "Overall, in this study, we found that LINC01133 is overexpressed in ectopic endometriosis lesions compared to the eutopic endometrium of women both with and without the disease." (PMID 34445100, 2021). "Given that EMT is also a feature of endometriosis we reasoned that LINC01133 may also be involved in the pathogenesis of endometriosis, and sought to investigate this in our study." (PMID 34445100, 2021). "Together this data indicates that LINC01133 may regulate actin remodeling in endometriosis epithelial cells via this pathway." (PMID 34445100, 2021). "Given that we did not see a classic E-cadherin to N-cadherin switch, and that expression changes for some EMT markers could not be validated, these data suggest that LINC01133 does not play a significant role in regulating EMT in endometriosis epithelial cells." (PMID 34445100, 2021).
esophageal squamous cell carcinoma (1 paper, 2025). Esophageal squamous cell carcinoma (ESCC) is a type of esophageal carcinoma (EC) that can affect any part of the esophagus, but is usually located in the upper or middle third. "It is demonstrated that LINC01133 acts as a tumor suppressor in gastric cancer, nasopharyngeal cancer, oral esophageal squamous cell carcinoma (ESCC), and colorectal cancer." (PMID 39744510, 2025).
gastric tumors (1 paper, 2018). "The down-regulation of PCAT18 and LINC01133 in GC implies that these lncRNAs may have a tumor suppressive function in the development of gastric tumors." (PMID 30518158, 2018).
laryngeal squamous cell carcinoma (1 paper, 2025). A squamous cell carcinoma that arises from the larynx. "LINC01133 is a lncRNA that has exhibited dichotomous roles in various malignancies but to the best of our knowledge, the role of LINC01133 in laryngeal squamous cell carcinoma (LSCC) has not been previously investigated." (PMID 39744510, 2025).
liver cancer (1 paper, 2023). An epithelial or non-epithelial malignant neoplasm that arises from the liver. "In GSE104462, LINC01133 was found to be upregulated by erastin in the liver cancer cell line HepG2." (PMID 38007473, 2023).
metastatic tumours (1 paper, 2019). "Additionally, the expression of SOX4 was increased in LINC01133 knockdown lung metastatic tumours, while the expression of LINC01133 was decreased in LINC01133 knockdown lung metastatic tumours." (PMID 31557401, 2019).
oral squamous cell carcinoma (1 paper, 2022). "In oral squamous cell carcinoma, a transcriptional regulatory mechanism was found to regulate LINC01133 expression." (PMID 35747817, 2022).
prostate carcinoma (1 paper, 2018). A carcinoma that arises from epithelial cells of the prostate gland. "LINC01133 was also down-regulated in esophageal, colon, and rectal cancers as well as in prostate cancer." (PMID 30518158, 2018).
tumor (28 papers, 2016 to 2025). "Our data of a role for LINC01133 in GC are in line with those from a recent study that showed an association of a reduced LINC01133 expression with aggressive tumor phenotypes." (PMID 30518158, 2018). "Interaction prediction assays with miRNA and luciferase reporter assays also demonstrated the action of LINC01133 as a sponge for the miRNA miR-30b-5p, negatively regulating it and, as a consequence, increasing the expression of the Rab3D protein, which is directly associated with tumor growth." (PMID 40863724, 2025). "The role of LINC01133 in ovarian and breast cancers remains contentious, as some studies suggest tumor-suppressive effects while others indicate possible pro-oncogenic activities." (PMID 39744510, 2025). "In vitro assays with Hela, ME-180, C33A, and M5751 human tumor cell lines showed, through LINC01133 silencing, qRT-PCR, and phenotypic migration and invasion assays, that LINC01133 modulates EMT processes and increases cell invasion and migration capabilities." (PMID 40863724, 2025). "Despite both promoter and suppressor tumor activities, LINC01133 predominantly acts as a tumor suppressor in GT." (PMID 40863724, 2025). "LINC01133, a lncRNA that has been identified as both an oncogene and a tumor suppressor, remains largely unexplored in terms of its molecular mechanisms." (PMID 40863724, 2025). "The results of several previous studies also indicated a double-edged sword-like properties for LINC01133 which can act as a tumor suppressor or an oncogene in a context-dependence manner." (PMID 39744510, 2025). "LINC01133 is up-regulated in PDAC and is associated with PDAC tumor growth, proliferation, migration, metastasis, and invasion." (PMID 38987572, 2024). "IF-FISH showed that LINC01133 and Arp3 were colocalized in the cytoplasm of tumor cells in PDAC tissue microarray." (PMID 38987572, 2024). "At same time, It was found that the expression of LINC02577 and LINC01133 increased in the blood extracellular vesicle of tumor patients, and LINC02577 was statistically significant." (PMID 37173624, 2023). "For example, LINC01133 exerts tumor suppressor effects in hepatocellular carcinoma not only through the competing endogenous RNAs (ceRNA) mechanism that involves binding to miR-199a-5p, but also by binding to the ANXA2 protein." (PMID 35747817, 2022). "The expression of linc01133 was positively related with tumor size (p = 0.03) and differentiation (p = 0.003)." (PMID 35017464, 2022). "LINC01133 appears to have a tissue-specific function, serving as either an oncogene or a tumor suppressor gene in various cancer types." (PMID 36371178, 2022). "Patients with high LINC01133 copy numbers in their tumors exhibited shorter tumor‐free survival than those with low LINC01133 copy numbers in their tumors." (PMID 34047479, 2021). "Because both the genomic copy numbers and the RNA expression of LINC01133 were increased in the tumors compared with those in the tumor‐adjacent tissues, we selected LINC01133 for further investigation." (PMID 34047479, 2021). "LINC01133 repressed cell proliferation, colony formation, invasion, migration, and tumorigenic ability in vitro and tumor formation and metastasis in vivo on tumor xenograft in nude mice." (PMID 33238475, 2020). "LINC01133 plays opposite roles in several types of cancers, as either an oncogene or tumor suppressor." (PMID 32792860, 2020). "QPCR analysis found that the levels of LINC01133 in tumor tissues formed from sh-LINC01133 cells were lower than in tumors formed in the control group." (PMID 26840083, 2016). "In CRC, LINC01133 appears to have a tumor-suppressive effect." (PMID 40863724, 2025). "The si-LINC01133 1# group showed decreased tumor size and weight compared to the si-NC group." (PMID 38987572, 2024). "LINC01133 may execute its biological function in a tissue-specific manner as it has diverse expressions and effects on tumor progression in different cancers." (PMID 38987572, 2024).
tumor (continued). "In both these studies, LINC01133 acted as a tumor suppressor via the ceRNA mechanism." (PMID 35747817, 2022). "However, considering that LINC01133 acts as a tumor suppressor gene in some cancers, importing functional LINC01133 is also a viable treatment option." (PMID 35747817, 2022). "Moreover, in the mouse tumor xenografts, linc01133 induced increased YAP1 expression both in the cytoplasm and in the nucleus, which were greatly ablated by simultaneous YES1 knockdown." (PMID 35017464, 2022). "Collectively, LINC01133 could promote tumor growth and EMT in vivo and facilitate peritoneal metastasis, which provides adequate conditions for PDAC progression and metastasis." (PMID 33824474, 2021). "In addition, the LINC01133 copy number had a positive relation with LINC01133 expression in the tumors relative to that in the tumor‐adjacent tissues." (PMID 34047479, 2021). "In this study, we demonstrated that LINC01133 was significantly decreased in GC tissues and cell lines, and LINC01133 inhibited tumor growth, the EMT process, and metastasis both in vitro and in vivo, suggesting that LINC01133 can act as a tumor suppressor in GC." (PMID 30134915, 2018). "Our findings of a tissue-specific down-regulation of PCAT18 and LINC01133 in gastric and other gastrointestinal cancers imply that these lncRNAs may have a tumor suppressive function in the development of these tumor entities." (PMID 30518158, 2018). "Therefore, The results of the in vitro and in vivo experiments strongly suggest that LINC01133 is a novel tumor suppressor in GC progression and metastasis." (PMID 30134915, 2018). "LINC01133 was upregulated and could promote tumor cell proliferation in PDAC." (PMID 38987572, 2024). "Moreover, YES1 ablation greatly hindered linc01133-induced tumor growth." (PMID 35017464, 2022). "In in vitro experiments, negative regulation of LINC01133 by TGF-β, an inherent tumor promoter, was observed." (PMID 40863724, 2025). "RNAscope assay confirmed that LINC01133 was overexpressed in the HCC tumors compared with the tumor‐adjacent tissues and mainly existed in cytoplasm of the tumor cells." (PMID 34047479, 2021). "LINC01133 overexpression in HCC cells promoted proliferation and aggressive phenotypes in vitro, and facilitated tumor growth and lung metastasis in vivo, whereas LINC01133 knockdown had the opposite effects." (PMID 34047479, 2021). "According to the intersection of up-regulated lncRNAs in GSE18842 and GSE19188, seven lncRNAs (LINC00511, LINC01133, DUXAP10, LINC01296, BBOX1-AS1, AFAP1-AS1 and LINC01116) were found to be highly expressed in NSCLC tumor tissues in both datasets." (PMID 33931086, 2021). "According to relative LINC01133 expression in tumor tissues, the 68 NSCLC patients were classified into two groups: the high LINC01133 group (n = 34, fold-change ≥ mean ratio); and the low LINC01133 group (n = 34, fold-change ≥ mean ratio)." (PMID 26840083, 2016). "RNA-Seq sequencing identified strong evidence of gene modulation linked to metastasis (such as GDF15) by LINC01133, along with reciprocal regulation of LINC01133 expression by GDF15, identified through GDF15 silencing assays in CAL27, HN4, and 293FT tumor cell lines." (PMID 40863724, 2025). "AC083841.1, LINC01133, SH3PXD2A-AS1, and AC015660.1 were highly expressed in tumor samples, while AC022098.1, PAN3-AS1, AF111169.3, AC005332.4, LRRC8C-DT, ZNF236-DT, SUGT1P4-STRA6LP, AC096733.2, TRAF3IP2-AS1, AL390208.1, AC087501.4, AC090114.2, and AC005332.6 were mainly expressed in normal samples." (PMID 36618967, 2022). "Both LINC01133 and PTGER4 genes are related with p21, which is a well-known tumor-suppressor gene." (PMID 31856825, 2019).
cancer (19 papers, 2018 to 2025). A tumor composed of atypical neoplastic, often pleomorphic cells that invade other tissues. "In this review, we describe the molecular mechanism underlying the various biological functions of LINC01133, its role in cancer, and future research directions." (PMID 35747817, 2022). "Impaired expression of LINC01133 has been associated with the regulation of EMT in cancer." (PMID 34445100, 2021). "Long intergenic non-coding RNA 01133 (LINC01133), located on chromosome 1q23.2, has gained considerable attention due to its dysregulated expression and involvement in numerous cancer types." (PMID 39744510, 2025). "Previously, LINC01133 has emerged as an important cancer-related gene and a growing number of studies have gradually uncovered its role in cancer." (PMID 38987572, 2024). "An increasing number of reports have revealed subsequently that LINC01133 is deregulated in many human cancers." (PMID 36371178, 2022). "Based on its genomic location (intergenic), structural features, and subcellular localization, LINC01133 regulates biological processes in cancers via multiple mechanisms that are activated simultaneously." (PMID 35747817, 2022). "The ceRNA mechanism of regulation by LINC01133 is commonly observed during the regulation of malignancy of cancers." (PMID 35747817, 2022). "The complex and diverse molecular regulatory mechanisms of LINC01133 determine the molecular basis for its functional specificity in different cancers." (PMID 35747817, 2022). "Over-expression of linc01133 greatly enhanced, while knocking-down of linc01133 hindered, the proliferation and colony formation potency of the cancer cells." (PMID 35017464, 2022). "LINC01133 can affect cancer metastasis through regulation of epithelial-mesenchymal transition program." (PMID 36042493, 2022). "Of these, LINC01133 has been found to be a regulator of cancers of the digestive, female reproductive, urinary, respiratory, and skeletal systems." (PMID 35747817, 2022). "LINC01133 is a long intergenic non-coding RNA that regulates malignancy in several cancers, including those of the digestive, female reproductive, respiratory, and urinary system." (PMID 35747817, 2022). "LINC01133 is located in both the nucleus and cytoplasm, and this subcellular localization depends on the type of cancer." (PMID 35747817, 2022). "There is accumulating evidence that the downstream targets and signaling pathways regulated by LINC01133 contributes to the malignant behavior of multiple types of cancer cells." (PMID 34047479, 2021). "TFF1, IGFBP7, JUNB, CLDN18 and LINC01133 genes were among the top genes of the primary cancer cells." (PMID 34055623, 2021). "Recent evidence has indicated that the novel lncRNA LINC01133 plays an important role in cancer progression and metastasis." (PMID 30134915, 2018). "The expression levels of LINC01133 vary across different types of cancer, suggesting that there is tissue-specific regulation of its expression." (PMID 30134915, 2018). "These insights highlight the central role of exosomal LINC01133 in PDAC and propose that targeting LINC01133 could be an effective approach for treating this cancer." (PMID 39925739, 2025). "LINC01133 was also reported to participate in the development of various types of cancer." (PMID 38007473, 2023). "Therefore, elucidating the specific mechanism of regulating LINC01133 expression in tumors is of great significance for cancer therapies targeting the abnormal expression of LINC01133." (PMID 35747817, 2022). "The abnormal expression of LINC01133 is extremely common in cancers." (PMID 35747817, 2022). "Indeed, several studies have reported that linc01133 functions as a ceRNA for several miRNAs in different cancer types." (PMID 35017464, 2022). "Therefore, in cancers where LINC01133 exerts a carcinogenic effect, LINC01133 is a potential target for cancer therapies." (PMID 35747817, 2022).
cancer (continued). "In addition to endogenous LINC01133 present in cancer cells, exogenous LINC01133 present in exosomes in the TME can also affect the malignancy of cancer cells." (PMID 35747817, 2022). "In addition to the validation of commonly studied protein gene targets, we also identified two specific LincRNAs, MEG3 and LINC01133, which specifically represented one of the cancer cell clusters respectively." (PMID 34055623, 2021). "In fact, LINC01133 could sufficiently promote phenotypic and growth features of cancer stem cells." (PMID 36042493, 2022). "Thus, LINC01133 expression appears to be tissue-specific and varies by cancer type." (PMID 33824474, 2021). "Similar to PCAT18, LINC01133 is also highly expressed in normal stomach tissues based on GTEx data implying that its deregulation in normal stomach tissue may play a role in the fate of cells and cancer progression." (PMID 30518158, 2018). "LINC01133 positive and MEG3 positive cells were well separated in the integrated cancer cell data and showed little overlap." (PMID 34055623, 2021). "Therefore, we suspected that LINC00943, LINC00174, DSCAM-AS1, MAGI1-IT1, MIR4458HG and LINC01133 may have similar regulatory roles in the proliferation and differentiation of stromal and neutrophil cells as those in the proliferation and differentiation of cancer cells." (PMID 38919957, 2024).
gastrointestinal tumors (1 paper, 2018). "Altogether, we showed a decreased tissue-specific expression of PCAT18 and LINC01133 lncRNAs in GC and other gastrointestinal tumor tissues, suggesting a role of these lncRNAs in the development of gastrointestinal tumors." (PMID 30518158, 2018).
LINC01133 also shares sentences with these, for which no sentence is quoted: nasopharyngeal carcinoma (3 papers); lung adenocarcinoma (2); cancers of the digestive system (1); cervical squamous cell carcinoma (1); colon adenocarcinoma (1); colon cancer (1); endocervical adenocarcinoma (1); endometrial carcinoma (1); non-small cell lung carcinoma (1); ovarian serous cystadenocarcinoma (1); rectal cancer (1); rectum adenocarcinoma (1); stomach adenocarcinoma (1); triple-negative breast carcinoma (1).